COL4A2 (collagen type IV alpha 2 chain)
Diseases named in the same sentence as COL4A2 in open-access papers (continued):
Sharing a sentence is not in itself a finding about the gene and the disease.
lung carcinoma (5 papers, 2017 to 2025). "Recently studies revealed that COL4A2 is involved in the pathogenesis and progression of esophageal cancer, lung cancer, and prostate cancer and other cancers." (PMID 27906681, 2017). "In addition, COL4A2 is significantly overexpressed in tissues obtained from brain metastases of lung cancer and melanoma patients." (PMID 27906681, 2017). "In addition to Laminins, in dECM-tumors we also observed elevated deposition of Alpha-2 Chain of Type IV Collagen (COL4A2), another major component of the tumor microenvironment with potential involvement in the pathogenesis and progression of multiple cancer types, including lung cancer." (PMID 40166338, 2025). "A similar population of α-SMA positive cells expressing collagenous matrisome genes COL4A1 and COL4A2 were discovered in idiopathic pulmonary fibrosis (IPF) and lung cancer tissues." (PMID 38727265, 2024). "We noticed that tip cells from RAECs and a breach EC phenotype in lung cancer shared similar expression patterns, including the upregulation of tip cell markers and collagen remodeling markers (COL4A1, COL4A2)." (PMID 38997406, 2024).
schizencephaly (5 papers, 2019 to 2025). "Individuals with COL4A1/2 were also reported to manifest with schizencephaly (8% [24/290] of individuals with COL4A1 and 13% [4/31] with COL4A2) and cerebellar atrophy (5% [14/290] of individuals with COL4A1 and 3% [1/31] with COL4A2)." (PMID 35699195, 2022).
aneurysm (4 papers, 2014 to 2025). Bulging or ballooning in an area of an artery secondary to arterial wall weakening. "COL4A2 encodes the collagen type IV α2 chain, and its mutations have been linked to various cardiovascular diseases, including aneurysms." (PMID 41497804, 2025). "Genetic studies have shown that COL4A2 mutations can lead to congenital aneurysms." (PMID 38685029, 2024). "Compared to familial intracranial aneurysms, abnormal COL4A2 expression in sporadic aneurysms may be associated with aneurysm development." (PMID 38685029, 2024). "Variants of collagen genes, including COL4A2, have been implicated in sporadic AD pathogenesis, and COL4A1 and COL4A2 mutations are associated with a broader spectrum of cardiovascular, renal, ophthalmological, and muscular abnormalities as well as aneurysms." (PMID 41497804, 2025). "In addition, COL4A2 is essential for aneurysm development according to a label-free quantitative proteomics study of human intracranial aneurysms." (PMID 38685029, 2024). "The protein expression levels of COL4A2, MYLK, and VCL were decreased after SMCs were intervened with TNF‐α, consistent with the results from mass spectrometry on aneurysm samples (E‐G)." (PMID 33389819, 2021). "We found that COL4A2, MYLK, VCL, and TAGLN may be related to aneurysm development." (PMID 33389819, 2021).
Leukoencephalopathy (4 papers, 2018 to 2025). This term describes abnormality of the white matter of the cerebrum resulting from damage to the myelin sheaths of nerve cells. "Several genome-wide association studies (GWAS) have identified single-nucleotide polymorphisms (SNPs) in the following genes: TRIO, PRKG1, ANK1, COL4A2, NTN1, and ASTN2 that were associated with increased risk of MTX-induced neurotoxicity and leukoencephalopathy on imaging in patients with ALL." (PMID 41029358, 2025).
renal fibrosis (4 papers, 2022 to 2024). A final common manifestation of a wide variety of chronic kidney diseases characterized by glomerulosclerosis and tubulointerstitial fibrosis. "COL4A2, CXCL1, TIMP1, VCAM1, and VEGFA are promising diagnostic biomarkers of tissue and serum for renal fibrosis." (PMID 37266443, 2023). "In short, COL4A2, CXCL1, TIMP1, VCAM1, and VEGFA are promising diagnostic biomarkers of tissue and serum for renal fibrosis, which is helpful for the early diagnosis and treatment of patients with renal fibrosis." (PMID 37266443, 2023). "In addition, we also showed the MRTF-dependent behavior of Col4A2, a basement membrane component, the expression of which was shown to increase in renal fibrosis." (PMID 38891116, 2024). "COL4A2, CXCL1, TIMP1, and VCAM1 have all been shown to be elevated in renal fibrosis, which is consistent with the findings of our experimental study." (PMID 37266443, 2023). "Five genes (COL4A2, CXCL1, TIMP1, VCAM1, and VEGFA) were subsequently identified as biomarkers for renal fibrosis through machine learning, and their expression levels were confirmed by validation cohort data sets and in vitro RT-qPCR experiment." (PMID 37266443, 2023).
triple-negative breast carcinoma (4 papers, 2017 to 2025). An invasive breast carcinoma which is negative for expression of estrogen receptor (ER), progesterone receptor (PR), and human epidermal growth factor receptor 2 (HER2). "Similarly, Type IV collagen promotes the expansion of head and neck squamous carcinoma cancer stem cells (HNSC-CSCs), and inhibiting collagen type IV alpha 2 (COL4A2) by siRNA significantly reduces the expansion and metastasis of triple-negative breast cancer (TNBC)." (PMID 37784157, 2023).
cataract (3 papers, 2023 to 2024). Partial or complete opacity of the crystalline lens of one or both eyes that decreases visual acuity and eventually results in blindness. "Based on this, it was speculated that PDGFRB and CDKN1A were promoting genes, and PTEN, CANX, COL4A2, EIF2S1, and NPM1 were suppressing genes in cataract pathogenesis." (PMID 38662949, 2024).
chronic kidney disease (3 papers, 2010 to 2022). Impairment of the renal function secondary to chronic kidney damage persisting for three or more months. "Moreover, in patients with chronic kidney disease, DNA methylation level of Col4a1 and Col4a2 genes was found to be significantly lower compared to healthy subjects and in correlation with increased mRNA and protein expressions." (PMID 33777319, 2021). "There is evidence that HIF1A can directly regulate and inhibit the expression of Collagen 4 subunit A2 (COL4A2) in renal cells, which can be used to treat acute kidney injury and protect against chronic kidney disease (CKD)." (PMID 35721542, 2022).
Cirrhosis (3 papers, 2020 to 2022). A chronic disorder of the liver in which liver tissue becomes scarred and is partially replaced by regenerative nodules and fibrotic tissue resulting in loss of liver function. "In this study, the transcriptional levels of COL4A1 and COL4A2 in approximately 500 clinical samples from two GEO datasets and one TCGA dataset were significantly increased in cirrhosis and HCC." (PMID 31905170, 2020). "The result showed that among the six Col IV isoforms, only COL4A1 and COL4A2 were significantly upregulated from liver preneoplastic lesions (cirrhosis and dysplasia) to HCC." (PMID 31905170, 2020). "COL4A2 was also increased in cirrhosis (fold change =3.412, p = 2.02E-6), liver cell dysplasia (fold change =2.223, p = 1.35E-4), and HCC (fold change =3.154, p = 7.07E-7) compared to normal tissues." (PMID 31905170, 2020). "Previous studies have found that COL4A2 may be a tumor biomarker that promotes tumor metastasis and proliferation, which is highly expressed in liver preneoplastic lesions, such as fibrosis and cirrhosis." (PMID 36246593, 2022).
hypertrophic cardiomyopathy (3 papers, 2021 to 2022). A condition in which the myocardium is hypertrophied without an obvious cause. "Besides, Col4a2, a basal lamina protein associated with interstitial fibrosis, is predicted to regulate fibrosis in hypertrophic cardiomyopathy." (PMID 36003513, 2022).
idiopathic pulmonary fibrosis (3 papers, 2022 to 2024). Idiopathic pulmonary fibrosis (IPF) is a nonneoplastic pulmonary disease that is characterized by the formation of scar tissue within the lungs in the absence of any known cause. "Given the contradictory role of type IV collagen in pulmonary fibrosis development, we next questioned how deeply Col4a1 and Col4a2 are associated with a regulation of fibrosis-related processes." (PMID 35625754, 2022). "Moreover, few studies have explored the role of Col4a1 and Col4a2 in pulmonary fibrosis via TGF-β pathway modulation." (PMID 35625754, 2022). "The validation of genes related to non-allergic bleomycin-induced pulmonary fibrosis on asthmatic/fibrotic lungs allowed us to identify new universal genes (Col4a1 and Col4a2) associated with the development of lung fibrosis regardless of its etiology." (PMID 35625754, 2022). "Comparison of interactome of Col4a1 and Col4a2 with interactome of Col1a1, a key molecular determinant of pulmonary fibrosis, revealed their significant similarity—approximately 77% of partner genes of Col4a1 and Col4a2 retrieved from STRING database were found to be first neighbors of Col1a1." (PMID 35625754, 2022). "The chronization of asthma and development of lung fibrosis was shown to either not affect observed asthma-driven upregulation of the genes, as in the case of Col1a1, Col4a1, and Col4a2, or downregulate the expression of Thbs2 and Tyrobp almost to the level of healthy control." (PMID 35625754, 2022).
liver cirrhosis (3 papers, 2020 to 2023). "The mRNA expression levels of COL4A1 and COL4A2 were significantly upregulated in patients with liver cirrhosis and HCC tissues in two datasets." (PMID 31905170, 2020). "Apart from this, COL4A1 and COL4A2 were in the top 5% over-expression gene rank of liver cirrhosis and HCC in both datasets." (PMID 31905170, 2020). "Both COL4A1 and COL4A2 were found in the top 5% of the over-expression-gene-rank of liver cirrhosis and the top 3% of HCC." (PMID 31905170, 2020).
myocardial infarction (3 papers, 2016 to 2019). Gross necrosis of the myocardium, as a result of interruption of the blood supply to the area, as in coronary thrombosis. "In analysis limited to 60 CAD genes, we detected strong associations with COL4A2/COL4A1 that also previously showed associations with myocardial infarction and arterial stiffness, as well as coronary artery calcification." (PMID 28642624, 2017). "Associations of COL4A1/COL4A2 reported from meta-analysis of GWAS for coronary artery calcification are of special interest since these genes also showed associations with myocardial infarct in contrast with most other loci associated with coronary artery calcification." (PMID 28642624, 2017). "Our results demonstrate that the TortA-associated variants in COL4A2 are independent of CAD, myocardial infarction, and blood pressure, and point to a selective role of COL4A2 rather than COL4A1 in the retinal vessels." (PMID 31597446, 2019).
Obesity (3 papers, 2021 to 2022). Accumulation of substantial excess body fat. "Taken together, CD36, COL4A2, GLUL, and ACACB were considered as core genes closely related to obesity and T2DM." (PMID 34085602, 2021). "Taken together, CD36, GLUL, COL4A2, and ACACB were considered as core genes in human adipose tissue with obesity or T2DM." (PMID 34085602, 2021). "We plan to examine the relationship between COL4A2 expression and the pathogenesis and progression of T2DM and obesity in future studies." (PMID 34085602, 2021). "We anticipate identifying the genes closely related to obesity and T2DM and further investigate their relationship with the CD36, COL4A2, GLUL, and ACACB as they may be target genes for future therapies." (PMID 34085602, 2021).
pancreatic cancer (3 papers, 2018 to 2025). "We found that Ccn1‐deficient pancreatic cancer cells exhibit reduced expression of collagens, including Col4a1, Col4a2, Col5a1, Col6a1, Col6a2, Col6a3, and Col8a1." (PMID 40287974, 2025). "Similarly, mRNA levels of Col5a1, Col6a1, Col6a2, Col6a3, and Col8a1 were significantly reduced in Ccn1‐deficient pancreatic tumors, while Col4a1 and Col4a2 were unaffected." (PMID 40287974, 2025). "Examination of the relationship between gene expression and prognosis using the R2 platform showed that ITGB1 was significantly correlated with the prognosis of pancreatic cancer (p = 0.036), but COL4A1 (p = 0.084), COL4A2 (p = 0.121), and ITGA5 (p = 0.285) were not." (PMID 35648752, 2022).
periodontitis (3 papers, 2024 to 2025). An acute or chronic inflammatory process that affects the tissues that surround and support the teeth. "Overall, the findings demonstrate that COL4A2, CYR61, and CXCL6 have strong diagnostic potential, highlighting their utility as biomarkers for periodontitis." (PMID 40539067, 2025). "Comprehensive bioinformatics analysis identified COL4A2, CYR61, and CXCL6 as key genes associated with oxidative stress in periodontitis." (PMID 40539067, 2025). "For further investigate the candidate regulatory mechanisms of key crosstalk genes (ITGAX and COL4A2) shared by intracranial aneurysms and periodontitis, we constructed a target gene-TF network." (PMID 38685029, 2024). "Specifically, we identified two genes, COL4A2 and CXCL6, which are closely associated with oxidative stress and may play a critical role in the pathogenesis of periodontitis." (PMID 40539067, 2025). "Further research is needed to determine whether COL4A2 can serve as a potential therapeutic target or a focus for mechanistic studies in periodontitis." (PMID 40539067, 2025). "However, the specific mechanisms linking COL4A2 to oxidative stress in periodontitis remain unclear." (PMID 40539067, 2025). "Therefore, we hypothesize that the immune process mediated by ITGAX and COL4A2 is central to the co-morbid mechanism of intracranial aneurysm and periodontitis." (PMID 38685029, 2024). "COL4A2 and CXCL6 were identified as potential therapeutic targets for the treatment of periodontitis." (PMID 40539067, 2025). "The results confirmed that the expression levels of COL4A2, CYR61, and CXCL6 were significantly different between periodontitis patients and the control population (P < 0.05)." (PMID 40539067, 2025). "Among these genes, COL4A2 and CXCL6 showed elevated expression levels in the gingival tissues of periodontitis rats." (PMID 40539067, 2025). "Additionally, qPCR analysis confirmed the upregulated expression of COL4A2 and CXCL6 in gingival tissues of periodontitis-induced rats." (PMID 40539067, 2025). "Additionally, while we identified a correlation between oxidative stress activity and the expression of COL4A2 and CXCL6, the precise mechanisms by which these genes influence oxidative stress and contribute to the progression of periodontitis remain unclear." (PMID 40539067, 2025). "Although no direct evidence links COL4A2 to periodontitis, its significant role in endothelial cells suggests a potential mechanism by which it may mitigate oxidative stress-induced damage in periodontal tissues." (PMID 40539067, 2025).
prostate carcinoma (3 papers, 2015 to 2019). A carcinoma that arises from epithelial cells of the prostate gland. "COL4A2 is highly expressed in CD133+/CD44+ prostate cancer spheroids; Head and neck CSCs grown on type IV collagen-coated plates grow much faster than in suspension and maintain CSC traits." (PMID 31334229, 2019). "Previous literature indicated that these six genes, i.e., CAV1, COL4A2, HSPB1, ITGB3, MAP1A and MCAM, were linked to prostate cancer progression." (PMID 26158290, 2015). "Furthermore, several studies suggested that COL4A2 may play a role in the pathogenesis of prostate cancer, epithelial ovarian cancer, colorectal cancer, and uterine leiomyoma." (PMID 27906681, 2017). "In this study, we selected six genes, that had additionally been independently reported to be related to prostate cancer progression, CAV1, COL4A2, HSPB1, ITGB3, MAP1A and MCAM." (PMID 26158290, 2015).
Retinal hemorrhage (3 papers, 2016 to 2023). Bleeding located within the retina. "Retinal hemorrhage is more common in people who have the COL4A2 mutation." (PMID 37266443, 2023).
bladder cancer (2 papers, 2016 to 2021). "COL4A2 expression is positively correlated with the presence of macrophage and dendritic cell infiltration in cervical-cell cancer, while COL1A1 is positively correlated with tumor infiltration levels of macrophages and CD4+ T cells in bladder cancer." (PMID 33790966, 2021).
cervical cancer (2 papers, 2023 to 2024). A primary or metastatic malignant neoplasm involving the cervix. "The aberrant expression of many of them were positively correlated with the risk of cervical cancer, with the KM curves of four conveying significance, including COL4A1, COL4A2, COL5A1, and COL12A1, which implied their potential application in clinical diagnosis." (PMID 36683048, 2023).
colon carcinoma (2 papers, 2020). "In addition, it has been reported that COL4A1 and COL4A2 were associated with high risk of relapse in colon cancer." (PMID 32704448, 2020).
coronary artery calcification (2 papers, 2017 to 2022). Calcification of the coronary artery, used as a measure of coronary atherosclerosis, a risk factor for myocardial infarction. "GWAS studies suggest the involvement of rs4773144 COL4A2 gene variants in the development of CAD and coronary artery calcification and increased risk of MI." (PMID 35054067, 2022).
dyslexia (2 papers, 2018). A learning disorder characterized by an impairment in processing written words. "However, it is worth noting that GWAS for dyslexia have been under‐powered so far and variants with the strongest association to dyslexia (e.g., in genes RBFOX2, ABCC13, ZNF385D, COL4A2 and FGF18) failed to survive genome‐wide statistical scrutiny." (PMID 30218584, 2018).
endothelial dysfunction (2 papers, 2024). In vascular diseases, endothelial dysfunction is a systemic pathological state of the endothelium (the inner lining of blood vessels) and can be broadly defined as an imbalance between vasodilating and vasoconstricting substances produced by (or acting on) the endothelium. "To investigate if Col4a1 glycine mutations cause endothelial dysfunction via reduced collagen IV levels, we investigated vascular function in 3-month-old Col4a2+/em2Wtsi mice." (PMID 39216230, 2024). "The endothelial dysfunction occurs in early disease stages, 8 months before ICH in old age Col4a2+/em2Wtsi mice, and thus confirms it is an initial driver of CSVD." (PMID 39216230, 2024).
esophageal cancer (2 papers, 2017 to 2022). A primary or metastatic malignant neoplasm involving the esophagus. "Previously, it has been shown that COL4A2 is a diagnostic marker signature for esophageal cancer." (PMID 27906681, 2017).
Hypertension (2 papers, 2020 to 2022). The presence of chronic increased pressure in the systemic arterial system. "Risk factors include old age, hypertension and variants in the genes COL4A1/COL4A2 encoding collagen alpha-1(IV) and alpha-2(IV), here termed collagen-IV, which are core components of the basement membrane." (PMID 36205142, 2022).
Insulin resistance (2 papers, 2019 to 2021). Increased resistance towards insulin, that is, diminished effectiveness of insulin in reducing blood glucose levels. "The CD36, GLUL, MYH11, CD163, and COL4A2 genes were closely associated with weight loss, while the ACACB gene was closely related to insulin resistance." (PMID 34085602, 2021). "Rho family GTPase 3 (RND3), PARD6A, TLE2, FBLN2, COL4A1, and COL4A2 are novel biomarkers for the development of insulin resistance." (PMID 30678306, 2019).
intracranial aneurysms (2 papers, 2024). "For example, some studies have found that mutations in connective tissue‐related genes, such as COL4A1 and COL4A2, are associated with the pathogenesis of intracranial aneurysms." (PMID 38566524, 2024).
ischemic stroke (2 papers, 2016 to 2018). A stroke disorder caused by obstruction of blood flow to the brain, due to thrombotic (local blood clot formation) or embolic (due to a blood clot or other material traveling from another site) event. "With the exception of COL4A2, which has been linked to SVD, none of these loci have formerly been linked to ischemic stroke." (PMID 27073246, 2016).